IL33 (interleukin 33)
Diseases named in the same sentence as IL33 in open-access papers (continued):
Sharing a sentence is not in itself a finding about the gene and the disease.
tumor (continued). "IL-33 induces DCs to express semaphorin 4A, which is essential for the upregulation of IFN-γ production by tumor-infiltrating CD8+ T cells and the potent antitumor effects of IL-33." (PMID 36291105, 2022). "We investigated further the function of IL-33 in EMT, which plays a crucial role in tumor migration and invasion." (PMID 36110250, 2022). "On the other hand, the factors uniquely enriched in GEC (IL23A and WNT16B) and GPC (IL33 and SEMA7A) significantly promoted proliferation of radiated (8 Gy mC-) tumor cells only." (PMID 36261421, 2022). "Nuclear IL-33 in keratinocytes also promotes intrinsic TGF-β signaling through the SMAD signaling pathway, which constitutes a cell-autonomous tumor promotion mechanism in chronic inflammation." (PMID 35432341, 2022). "Collectively, these studies suggest that IL-25-mediated activation of ILC2s, and IL-33-mediated stimulation of Th2 cells, may act as independent parallel pathways to induce the production of IL-4 and IL-13 leading to the activation of MDSCs to suppress anti-tumour T cells and promote CRC." (PMID 36263033, 2022). "Emerging studies in the past decade have found IL-33 and IL-25 to either promote or inhibit CRC under different settings, and is likely dependent on the CRC subtype, tumour immunogenicity and the different immune cell populations involved." (PMID 36263033, 2022). "The blockade of IL-33 and/or ST2 results in tumor growth inhibition accompanied by the reduced accumulation of tumor-promoting Treg cells, M2-like macrophages, and IL17RB+ILC2s." (PMID 36291105, 2022). "Alongside being secreted by epithelium and endothelium, damaged cells also secrete IL-33 to activate ILC2s, attracting CD8+ T cells and shaping the tumour microenvironment." (PMID 35557940, 2022). "Thus, we next examined mast cells in IL-33 deficient gp130F/F mice, focusing on the two major subsets, connective tissue mast cells (CTMC) and mucosal mast cells (MMC), which differ in their histochemical and molecular characteristics, cytokine profiles and crucially, role in tumour progression." (PMID 35677533, 2022). "Since gp130F/F tumour development has been shown to be driven by IL-11 upregulation, attenuated Il11 expression and tumour growth seen in the compound mutant mice suggests that IL-33 might play a key role in the persistence of inflammation that leads to tumorigenesis." (PMID 35677533, 2022). "Expanded by IL-33, ILC2s in PC potentially produce chemokine CCL5, which promote the recruitment and accumulation of CD103+ DCs in tumor tissues and further activate antitumor immunity in CD8+T cells." (PMID 35409105, 2022). "IL-33 can recruit MDSCs and TAMs to support tumor growth but can also stimulate the infiltration of cytotoxic NK cells and CD8+T cells to regress tumor growth." (PMID 35122833, 2022). "Treg development, maintenance, accumulation, and immnosupression function in VAT and tumor tissues depend upon the expression of TCR, Foxp3, and IL-33." (PMID 35371055, 2022). "As ILC2s are activated thorough IL-33/ST2 signaling, we next sought to assess the source of endogenous IL-33 in 4T1/LM4 tumor-bearing mice." (PMID 35805039, 2022). "After the treatment, positive correlations of mSWAT with the levels of IL22, IL33, and TNF-α in the tumor tissue were found." (PMID 35237320, 2022). "Combined IL-33 treatment with PD-1 blockade promoted ILC2 anti-tumor responses and resulted in reduced tumor size and prolonged mouse survival." (PMID 34885076, 2021). "They reported that a decreased level of tumoral IL-33 and ST2 was correlated with enhanced tumor burden." (PMID 34209038, 2021). "IL-33 treatment in combination with PD-1 blockade reduced tumor growth in an ILC2-dependent manner, indicating that Tumor ILC2 was directly targeted by anti-PD-1." (PMID 34209038, 2021). "The IL-33/ST2 axis promoted enhanced cell oxidative phosphorylation, thereby further increasing M2 polarization gene expression and ultimately promoting tumor growth (P < 0.05)." (PMID 33628592, 2021).
tumor (continued). "The inflammatory proteases are released from mast cells and neutrophils which are recruited to the tumor microenvironment (TME), thereby promoting maturation of IL-33 to a higher active form within tumors." (PMID 34209038, 2021). "The combination of IL-33 with anti-PD-1 and anti-CTLA-4 antibodies further prolonged the survival of tumor-bearing mice." (PMID 34209038, 2021). "To investigate the role of the IL-33/ST2 axis in macrophages and its influence on tumor growth, we randomly injected B16 cells into the backs of WT, ST2−/−, and IL-33-overexpressing mice." (PMID 33628592, 2021). "Stimulation of macrophages with IL‐33 markedly increases MMP‐9 production, which remodels the extracellular components to facilitate tumor invasion." (PMID 34486239, 2021). "Tumor-derived IL-33 increases the number and function of CD103+CD8+ TILs, and a combination of IL-33 with the CTLA-4 and PD-1 immune checkpoint blockades synergistically prolonged the survival of tumor-bearing mice." (PMID 33467606, 2021). "The IL-33/ST2 axis can recruit Tregs in the TME and activate their immunosuppressive function, supporting tumor immune escape, favoring tumor growth." (PMID 34209038, 2021). "This study revealed an oncogenic role of IL‐33 by actively inducing M2‐like macrophage differentiation; thus, contributing to the formation of an immunosuppressive ESCC tumour microenvironment." (PMID 33305406, 2021). "Several lines of evidence demonstrate that IL-33/ST2 signaling in macrophages is involved in M2 polarization, immunosuppression, thus promoting tumor progression." (PMID 34209038, 2021). "Of these OPN, IL-33, CCL17, and MMP-9 were significantly reduced in the lung of 4T1 tumor-bearing mice treated with WECS." (PMID 34771120, 2021). "We performed immunohistochemical studies to assess the IL‐33, CD68 and CD206 levels in the tumour and non‐tumour tissue samples from patients with ESCC." (PMID 33305406, 2021). "(B) Western blot analysis of IL‐33 and CD206 expression in non‐tumour and tumour tissues, and GAPDH was used as a reference control." (PMID 33305406, 2021). "Among them, DDIT4 and HNF4A were highly expressed in tumor tissues, whereas ALOX15, IL33, and GDF15 were lowly expressed." (PMID 34434660, 2021). "In particular, IL-33 has been shown to promote the function of CD8+ T-cells and NL cells, thus promoting tumor eradication." (PMID 34071419, 2021). "The diagrammatic illustrations demonstrate our proposal to explain the major mechanism and the relationships between the molecules involved in the IL-33-p38MAPK-CXCR4-SDF-1 loop between the TME and the actual tumor." (PMID 34298657, 2021). "In these models, expression of IL-33 in tumors was a key inducer of CCL11 production and eosinophil-mediated anti-tumor responses." (PMID 33757558, 2021). "Nevertheless, the increased IL-33 expression in stromal components, such as CAF, creates a highly suppressive milieu for the immune response, thus contributing to the tumor progression and metastasis mainly by recruiting immune-suppressive TAM, MDSC, and Treg." (PMID 34209038, 2021). "We observed a strong correlation between the IL‐33 levels and the infiltration of M2‐like macrophages in ESCC tumours locally." (PMID 33305406, 2021). "Mechanistically, IL-33 is recognized by ST2 and activates NF-κB-MMP9-laminin pathway, thus aggravating tumor metastasis." (PMID 34895039, 2021). "IL-33 signals through its receptor ST2 are key for protective CTL responses to replicating viruses, and IL-33 signals critically augment CTL responses to artLCMV-vectored immunization and the resulting tumor control." (PMID 33763654, 2021). "(A) Representative images of IL‐33+ cell, CD206+ cell and CD68+ cell in non‐tumour and tumour tissue (scale bar = 50 μm)." (PMID 33305406, 2021).
tumor (continued). "In vivo experiments in pancreatic ductal adenocarcinomas (PDACs) have shown that IL-33 induces the activation of tissue-specific immunity, in particular of tissue resident ILC2s and CD8+ T cells, which limits tumor growth." (PMID 34680190, 2021). "Certain cytokines, like IL-33, a member of the IL-1 family, can regulate CRC progression by controlling the tumor microenvironment (TME)." (PMID 33435303, 2021). "A cytokine, interleukin 33 (IL33), released by CAFs, has been reported to induce treatment failure in HNSCCs and promote the stemness properties of via crosstalk between tumor cells and CAFs." (PMID 34298657, 2021). "The IL-33-enhanced-CXCR4 regulatory circuit involves SDF1/CXCR4 signaling activation and modulates tumor behavior." (PMID 34298657, 2021). "(C) IL‐33, CD206 and CD68 were measured by RT‐PCR in non‐tumour and tumour tissues; the correlation of CD206 and IL‐33 in ESCC tissues; N = 20, R2 = .54, P < .01." (PMID 33305406, 2021). "Accumulating evidence has indicated that IL-33 and its receptor ST2 (also known as IL1RL1) represent a key inflammatory pathway in tumor biology and immunology." (PMID 33953160, 2021). "IL‐33 is mainly located in the cytoplasm of ESCC cells, while CD68 and CD206 are mainly found in the tumour stroma." (PMID 33305406, 2021). "We further demonstrated that CD44 engagement by GPNMB activates in tumor cells the expression of several factors, including chemokines, e.g.: CXCL1, CXCL2, CCL2, CCL5, CCL7, cytokines: IL-6, IL-11, IL-33, and the IL-33 receptor: IL-1RL1, also named ST2." (PMID 34583655, 2021). "It was shown that 6 cytokines were upregulated more than 2-fold in 4T1 tumor-bearing mice compared to normal mice, namely OPN (osteopontin), CCL12 (chemokine (C-C motif) ligand 12), IL-33, CCL17, CCL6, and MMP-9." (PMID 34771120, 2021). "Thus, the effect of IL-33 on tumor progression might be cell type- and context-dependent." (PMID 32340025, 2020). "IL-33 is also able to increase PD-1 and PD-L1 expression at the cell surface of CD8+ T cells and tumor cells respectively." (PMID 33261061, 2020). "mRNA expression levels of IL-33, ST2, cytokines and chemokines in the cells and tumor tissues were examined using real-time PCR." (PMID 32340025, 2020). "In response to several stimuli such as IL-5, IL-33, CCL11, IFNγ and TNFα, eosinophils secrete cytotoxic proteins (MBP, ECP, EDN and granzymes), which can induce apoptosis of tumor cells." (PMID 33233582, 2020). "Flow cytometric analysis of tumor single cell suspensions showed a reduction in CD45+ cells, monocytes, CD8+ T cells and an increase in Tregs after treatment with IL-33 vs. vehicle in ∆dblGATA-1 mice." (PMID 32923137, 2020). "Exogenous IL-33 increased CD45+ leukocyte immune cells and decreased NK cell infiltration in tumours." (PMID 33308251, 2020). "M2 macrophages are alternatively activated macrophages that secrete IL-4, IL-10, IL-19, IL-33, TGF-β, and epithelial growth factor, all of which play an important role in promoting tumor growth and metastasis." (PMID 32993787, 2020). "IL-33 can promote the recruitment and the immunosuppressive functions of Treg cells expressing ST2, favoring tumor growth and immunoevasion." (PMID 33329534, 2020). "We found that IL-33 and ST2 were heterogeneously expressed in tumor tissues but expressed very low level in paracancerous tissues." (PMID 32003751, 2020). "The importance of IL-33 was explained by its capacity to increase the percentage of CD103+ DCs and CD8+ CD103+ T cells within the tumor, a sub-population important in the killing of malignant cells." (PMID 33261061, 2020). "On the other hand, IL-33 also stimulates infiltration of CD8+ T cells as well as natural killer cells, crucial for tumor elimination." (PMID 32363166, 2020). "In the CT26 cell engraftment tumor model with BALB/c mice, tumor growth was decelerated by treatment with IL-33 as compared to vehicle treatment (control)." (PMID 32923137, 2020).
tumor (continued). "Second, we showed that expression of IL-33 promotes tumor growth and TAM infiltration in intracranial xenografts, and that nuclear IL-33 is essential for its augmented effect on tumor growth." (PMID 33020472, 2020). "High frequencies of tumor-infiltrating ILC2 (TILC2) were found in “hot” tumors (enriched in CD8+ T cells), and correlated with better survival and high expression of IL-33." (PMID 33329534, 2020). "Binding of these chemokines to tumor cell-expressed CXCR2, which was sustained by the hypoxic TME created by IL-33, resulted in tumor cell apoptosis." (PMID 33329534, 2020). "IL-33 from the stroma (particularly endothelial cells) could support the survival and proliferation of tumor cells and even directly or indirectly contribute to the invasiveness of tumor cells, but it is unlikely that this occurs through modulation of the TIME." (PMID 33634017, 2020). "Other cytokines such as IL-33 enhances the expression of LFA1 and CD11b on eosinophils and ICAM1 on tumor cells facilitating their interaction." (PMID 33233582, 2020). "In the present study, we find that both IL-33 in stromal cells and the IL-33 receptor ST2L in tumor cells are aberrantly overexpressed in GC and serve as prognostic markers for poor survival." (PMID 31659258, 2020). "In murine hepatocellular carcinoma, tumor-derived IL-33 promoted the expansion of IFN-γ+ CD4+ and CD8+ T cells, increased CTL cytotoxicity and inhibited tumor growth." (PMID 33329534, 2020). "IL-33-treated tumor-bearing mice also showed an elevated proportion of CD4+FoxP3+ Tregs, due to the direct effect of IL-33 on Tregs expressing ST2." (PMID 33233582, 2020). "Considering that tumor localization has been reported to impact on immune response and CRC patient outcomes, we analyzed separately IL-33 and ST2 levels in left-sided or right-sided CRC." (PMID 31281317, 2019). "Several studies have found both the cytokine IL-33 and its receptor ST2, to be elevated in mouse and human CRC tissues, suggesting a potential role of this IL-33/ST2 pathway in tumor development and progression." (PMID 32010138, 2019). "Our findings from in vitro functional studies and from transcriptomic analyses of tumor tissues and CRC-isolated Tregs also indicate an implication of the IL-33/ST2 axis in the regulation of IL-17A expression by FOXP3+ Tregs and FOXP3− CD4+ T cells." (PMID 31165767, 2019). "In conclusion, our findings indicate that IL-33/ST2 signaling shapes the cellular and the inflammatory composition of the tumor microenvironment to promote intestinal tumorigenesis." (PMID 31165767, 2019). "The total content of IL-33 and ST2 were similar in tumor and normal tissue, however, it seems to depend, for IL-33, of the TNM stage." (PMID 31281317, 2019). "VS-4718 can inhibit the expression of immunosuppressive molecules such as IL-33 and CCL5, and reduce Tregs in the tumor environment." (PMID 31186061, 2019). "IL-33 is capable of remodeling the TME and stromal constituents, facilitating tumor growth and metastasis." (PMID 31681327, 2019). "Instead, IL-33 EO expressed increased levels of ICAM-1 and CD11b/CD18, and both molecules (mostly CD11b/CD18) polarized to the EO-tumor cell synapses." (PMID 31717819, 2019). "In mice with CRC, tumor-infiltrating Tregs preferentially upregulate IL-33 receptor (ST2), and IL-33/ST2 signaling positively correlates with tumor number and size." (PMID 31165767, 2019). "We were however further interested in the regulation of IL-33 responsivity of CD8+ T lymphocytes, as those represent a central cellular component in T cell mediated cytotoxicity and tumor immunity." (PMID 31396219, 2019). "In murine models, IL-33, depending on the TME, can recruit immune cells with pro-tumor effects, including MDSCs, TAMs, and Tregs, or it can prevent tumor development by stimulating activation and migration of NK and CD8+ T cells." (PMID 31057536, 2019).
tumor (continued). "By contrast, in a larger series, serum levels of IL-33 were demonstrated to be augmented in NSCLC patients and were correlated with tumor stages." (PMID 31130612, 2019). "Most studies attribute a protumorigenic role to the IL-33/ST2 axis in human, murine and in vitro models, with increased levels of IL-33 and ST2 transcripts in tumor vs. healthy tissue from CRC patients." (PMID 31281317, 2019). "Many reports focusing specifically on tumoral expression of IL-33 and ST2 have reported decreasing expression of these proteins with increasing tumor stage." (PMID 31231372, 2019). "In contrast, under anti-tumorigenic conditions, IL-33 directed the recruitment of NK cells and CD8+T cells, and increased production of IFN-γ that favor eradication of tumor cells." (PMID 30205617, 2018). "Regarding the mechanisms of IL-33/ST2 axis promoting tumorigenesis, increasing evidence suggests that one of the possibilities is through the activation of tumor stroma." (PMID 30559604, 2018). "Although most studies demonstrate that IL-33 promotes the development of CRC, the antitumor effect of IL-33 has also been reported at least in some tumor models." (PMID 30547011, 2018). "To investigate the potential role of IL-33/ST2L pathway in the tumor development in amouse model of CRC induced by CT26, we detected the messenger RNA (mRNA) and proteinlevels of IL-33 and sST2 or ST2L in the serum or tissue of tumor-bearing mice." (PMID 29950152, 2018). "Knockdown of IL-33 impaired the ability of Lnc-CAF to activate stromal fibroblasts and resulted in tumor regression." (PMID 30205617, 2018). "IL-33 induced the recruitment of macrophages into the TME where they produced prostaglandin E2 that further supported CRC stemness and tumor growth." (PMID 30205617, 2018). "We found that the expression levels of IL-33 and ST2 were decreased in tumor tissues compared with adjacent normal tissues." (PMID 29896199, 2018). "In detail, IL33 recruited macrophages into the cancer microenvironment and stimulated them to produce prostaglandin E2, which supported CRC stemness and tumor growth." (PMID 30532788, 2018). "The goal of this review is to summarize the hallmarks of IL-33 in cancer, both in terms of its pro-tumorigenic function targeting resident TH2 immune cells of the TME, and as a tumor suppressor molecule activating the competent TH1 immune cells." (PMID 30416507, 2018). "Regarding mechanisms of IL-33 promoting tumorigenesis, studies have suggested that that the IL-33 may regulate the expansion and function of different T cell subsets, ILC2s and nature killer (NK) cells, stimulate the process of angiogenesis, inhibit antitumor immunity and promote tumor cell growth." (PMID 30559604, 2018). "The MC38 tumors grew more rapidly and the tumor Ki67 and PCNA were expressed at higher levels in IL-33 transgenic mice than in wild-type mice." (PMID 30119635, 2018). "Analysis of mRNA expression of IL-33, ST2, and IL1-RAcP receptor accessory proteins using the Cancer Genome Atlas database showed that their expression levels were varied; however, IL-33 and IL1-RAcP mRNA levels correlated with tumor grade." (PMID 30205617, 2018). "Consistent with a pro-tumorigenic role, IL-33 and ST2 expression in patient tumor tissues were found to correlate with tumor progression in NSCLC patients." (PMID 30205617, 2018). "Although there has been considerable interest in the essential role of IL-33/ST2 axis in tumorigenesis, studies have provided contradictory results with both pro-tumor and anti-tumor effect reported." (PMID 30559604, 2018). "Exogenously administered recombinant mouse IL-33 significantly potentiates tumor burden and induces ST2 positive Tregs infiltrated into tumor masses." (PMID 30547011, 2018). "The effect of IL-33 on NK cells was also demonstrated by reduced presence of IFN-γ-expressing NK cells and increased NK cells that expressed IL-10 in tumor-bearing mice." (PMID 30112116, 2018).